CRP (C-reactive protein)
Diseases named in the same sentence as CRP in open-access papers (continued):
Sharing a sentence is not in itself a finding about the gene and the disease.
Sepsis (continued). "Both CRP and PCT levels did not affect the risk of 30-day all-cause mortality in patients with sepsis and septic shock." (PMID 37204560, 2024). "Baseline laboratory indices of systemic inflammation like C-reactive protein or white blood cell count were not significantly different between the surgery-only and sepsis group during the acute phase of inflammation." (PMID 38984201, 2024). "This study aims to evaluate the prognostic utility of CRP and PCT in pediatric sepsis by analyzing key clinical parameters, including the need for ionotropic support, steroid use, the incidence of acute kidney injury (AKI), the requirement for invasive ventilation, and patient outcomes." (PMID 39184737, 2024). "Hence, it is possible to use the parameters of WBC, CRP and ALB as indicators to estimate the likelihood of sepsis in patients, prior to the acquisition of PCT test results." (PMID 38771840, 2024). "The current criteria for diagnosis of sepsis are based on clinical signs and biomarkers such as procalcitonin (PCT) and C-reactive protein (CRP), which are not unique to sepsis and differ widely among individuals." (PMID 39430765, 2024). "In veterinary medicine, sepsis definition is still based on the SIRS criteria, and eventually on the presence of systemic inflammation detected by a rise in major acute phase proteins, like CRP in dogs." (PMID 38638640, 2024). "Previous studies have highlighted the individual roles of CRP and PCT in sepsis diagnosis." (PMID 39184737, 2024). "Furthermore, amongst the cases of confirmed sepsis, P-SEP was always greater than 2000 pg/mL, while C-reactive protein and procalcitonin values appeared lower than what was considered significant." (PMID 38790589, 2024). "A study including 31 preterm neonates with suspected sepsis showed that cfDNA, DNase I, nucleosome, and CRP concentrations were higher than those measured in non-septic preterms." (PMID 38256033, 2024). "In summary, our data identify cellular immune traits which differentiate Sepsis from No-Sepsis samples obtained from preterm babies, including those with low or undetectable CRP responses." (PMID 38195661, 2024). "Likewise, CRP, an acute-phase reactant, was found to correlate with the severity of sepsis and organ dysfunction, including AKI and higher mortality in pediatric sepsis." (PMID 39597864, 2024). "Plasma BMP6 levels did not correlate with procalcitonin and C-reactive protein levels in patients with SIRS or sepsis/septic shock." (PMID 39200147, 2024). "Conversely, PSP measurement combined with other biomarkers, such as CRP, and prognostic scores, such as the SOFA score and the national early warning score (NEWS), is recommended for screening and rapid diagnosis of infection, organ failure, and sepsis." (PMID 38892234, 2024). "Compared to traditional biomarkers such as C-reactive protein (CRP) and procalcitonin (PCT), miRNAs offer several advantages, including their early and sustained elevation during sepsis, as well as their stability in stored samples, making them attractive candidates for clinical use." (PMID 38928179, 2024). "Sepsis, central venous line (CVL) insertion, C reactive protein (CRP), and duration of NICU admission were significantly more common in the thrombotic group (p < 0.001) and were associated with a higher risk of thrombosis (ORs: 1.02, 7.7, and 1.11, respectively) (p < 0.001)." (PMID 39349608, 2024). "Although PCT is considered superior to CRP in a number of studies, it is not a definitive test for diagnosing sepsis because PCT levels can also be increased in other conditions." (PMID 38182736, 2024). "As an indicator of inflammation, CRP levels were significantly higher in nonsurvivors and patients with sepsis in our study." (PMID 38898407, 2024). "LDNs, PMN-MDSCs, MDSCs and CRP were more abundant in sepsis patients with shock compared to those without." (PMID 38609858, 2024).
Sepsis (continued). "Employing a PCT-based protocol for patients with sepsis in the intensive care unit (ICU) was not superior to the CRP-based protocol in guiding antibiotic therapy treatment." (PMID 38254218, 2024). "It has already been established that there is a correlation between the onset and development of sepsis and the level of RDW, which is an important predictor of death in patients with sepsis, and is closely related to inflammatory markers such as CRP." (PMID 38337856, 2024). "Given that BMP6 is not related to hepcidin and iron metabolism in severe illness, it is not unexpected that BMP6 plasma levels of patients with sepsis/septic shock were not correlated with CRP, procalcitonin, or white blood cell counts." (PMID 39200147, 2024). "Through five cases of sepsis patients, we showed that the number of bacteria is a novel useful biomarker that more sensitively reflects the therapeutic effect than currently available biomarkers (BT, WBC, CRP, presepsin, and IL-6)." (PMID 38216600, 2024). "nDNA had areas under the receiver operating characteristic (ROC) curves of 0.78 for sepsis and 0.76 for negative outcome, which were higher than those of the other DAMPs and additional biomarkers (CRP, IL-6, IL-8, and IL-10)." (PMID 39379599, 2024). "The prognostic value of CRP, PCT, and the neutrophil-to-lymphocyte ratio (NLR) was comprehensively investigated within a retrospective study including 146 patients with bloodstream infection and sepsis according to the sepsis-3 criteria." (PMID 37204560, 2024). "C-reactive protein (CRP), a non-specific marker of inflammation, is routinely used in laboratories around the world to assess inflammation in patients with sepsis." (PMID 39769181, 2024). "In our SIRS/sepsis cohort plasma, apoA-IV was not correlated with leukocytes, CRP, procalcitonin or IL-6." (PMID 39311203, 2024). "A meta-analysis of 39 studies comparing PCT and CRP revealed that the mean sensitivity of early-onset sepsis (EOS), late-onset sepsis (LOS), and both EOS and LOS combined are 73.6%, 88.9%, and 76.5% respectively suggesting that procalcitonin is superior to CRP." (PMID 38698211, 2024). "The sensitivity for confirming sepsis was found to be 95% for PSP, 75% for CRP, and 55% for PCT." (PMID 39295616, 2024). "The distinction between both entities is a clinical decision (according to SIRS/sepsis criteria) because the routine serum inflammatory markers, such as the C-reactive protein or the (differentiated) leukocyte count, are not determinants of the final outcomes." (PMID 39766526, 2024). "Biomarkers are helpful, but our study showed that 9.8% of all GPB sepsis had no elevated CRP concentration, specifically apparent for infants in the lower GWs." (PMID 38517573, 2024). "Therefore, compared with single markers, the biomarker panel of PCT, CRP, and SAA was more predictive of sepsis in severe polytrauma patients." (PMID 38182736, 2024). "CRP and PCT, the most commonly used clinical inflammatory markers, mainly reflect the pro-inflammatory host immune response, and are widely used in the diagnosis of sepsis, but their prognostic value is limited." (PMID 38799147, 2024). "MDSCs performed similarly to CRP and PCT in diagnosing infection or sepsis." (PMID 38609858, 2024). "Whilst host response characteristics and clinical outcomes have previously been used to sub-phenotype patients with suspected BSI or sepsis, CRP response trajectories have not been described in this detail to our knowledge." (PMID 38599549, 2024). "CRP was significantly higher in patients with GN sepsis or NEC (median CRP 4.4 g/dl, IQR 2.1–11.0) compared to patients with no sepsis [median CRP 0.1 g/dl, IQR 0.1–0.4 (p < 0.05)] or clinical sepsis [median CRP 0.12 g/dl, IQR 0.1–1.2 (p < 0.05)]." (PMID 38312920, 2024). "Interestingly, feature importance highlights the role of CRP and APACHE II in both SIRS and sepsis populations." (PMID 38489347, 2024).
Sepsis (continued). "Levels of presepsin are significantly higher in neonates with sepsis than in healthy ones, and they increased earlier than PCT or CRP; the rise in blood values of CRP and PCT is similarly high during the early phase of infection, but presepsin alone decreases with antibiotic treatment." (PMID 38254697, 2024). "The authors found that the combinations of CRP, lymphocytes count (LymC), and platelet count (PLTC) can be used to determine the likelihood of sepsis, however without exploring the association of these parameters with the patient survival for each population." (PMID 38489347, 2024). "The postoperative period was complicated by sepsis with coagulase-negative staphylococcus and rising C-reactive protein (CRP) which necessitated the advancement of antibiotics as per the sensitivity pattern and was given for a total of 10 days." (PMID 39429276, 2024). "From a total of 361 consecutive patients with sepsis or septic shock, 12 patients without CRP measurement on day 1 were excluded." (PMID 37204560, 2024). "Commonly infection markers in clinical settings like C-reactive protein (CRP) and procalcitonin (PCT) show increased responses to non-infectious stimuli within the first 48 hours of birth, making them unsuitable for early-onset sepsis (EOS) diagnosis." (PMID 39193501, 2024). "According to our mortality risk predictive model for sepsis, eleven indicators, including a history of CHD, NLR, RDW, lactic acid, PT, PCT, CRP, ALT, Tbil, and IL6 were independent predictors of poor prognosis in patients with sepsis, while the LYMP was a protective factor." (PMID 38765257, 2024). "Since SAA, CRP, and PCT were found to be independent predictors of sepsis from the result of multiple logistic regression, we need to determine whether the combination of these three biomarkers into a single bioscore could improve the diagnostic performance." (PMID 38182736, 2024). "One study suggests that IL-6 predicts treatment success in patients with non-surgical sepsis more effectively within first 48–72 h than PCT or CRP." (PMID 39589972, 2024). "The CD86%, neutrophil count, CRP/ALB, NLR, IL-6, IL-10, sIL-2R, CRP, and PCT levels were significantly higher, and the HLA-DR%, lymphocytes, PLT, and ALB levels were significantly lower in the sepsis group than in the non-sepsis group (all P<0.05)." (PMID 38603712, 2024). "Additionally, we investigated the relationship between sTREM-1 and other essential biomarkers in sepsis, including IL-6, lactate, PCT, and CRP." (PMID 39655134, 2024). "Clinical data, clinicians’ criteria and other late markers of organ dysfunction (lactate, creatinine, hypotension) or unspecific inflammation markers (leucocytes, CRP, etc.)are not useful to triage ED patients with a potential infection leading to sepsis." (PMID 39559359, 2024). "Initial investigations in acute PJI without evidence of sepsis include C-reactive protein (CRP), full blood count (FBC), renal function, and plain radiographs of the affected joint." (PMID 39655120, 2024). "Presepsin and PCT were able to discriminate the diagnosis septic shock from sepsis, whereas CRP was not shown to discriminate septic shock from sepsis." (PMID 37204560, 2024). "To date, CRP and PCT are quite widely used and studied biomarkers during sepsis in recent studies." (PMID 38182736, 2024). "In addition to these criteria, a recent study demonstrated that using inflammatory markers, such as C-reactive protein (CRP), procalcitonin (PCT), and neutrophil-to-lymphocyte ratio (NLR), in the early detection of sepsis was effective." (PMID 39336599, 2024). "According to the literature, CRP can be deemed a dependable adjunctive tool for suspecting sepsis, despite its nonspecific nature." (PMID 38907854, 2024). "The effectiveness of using four biomarkers (CRP, lactate, MR-proADM, and PCT) in identifying the various types of organ failure outlined in SOFA was evaluated in a cohort of patients presenting with infection, sepsis, or septic shock." (PMID 38891025, 2024).
Sepsis (continued). "The group S (sepsis) exhibited considerably inferior levels of CRP to group D (non-sepsis) (Z = −4.057, P < 0.001)." (PMID 38947447, 2024). "A comparison of laboratory test results revealed that the international normalised ratio (INR), prothrombin time (PT), D-dimer levels, CRP levels, and lactate levels were significantly higher in patients with sepsis than in those without sepsis." (PMID 38898407, 2024). "We observed six parameters within our core signature which demonstrated rapid temporal changes between sepsis and post-sepsis, in both ‘No CRP rise’ and ‘CRP > 10’ cohorts." (PMID 38195661, 2024). "Based on area under the curve-values from receiver operating characteristic analyses, the SeptiCyteTM Lab test reportedly outperformed the infection marker procalcitonin (PCT) but, conspicuously, not CRP in discriminating sepsis from SIRS." (PMID 39434093, 2024). "Moreover, the best predictive performance for this type of sepsis was obtained by the combinations of biomarkers WBC, CRP, and fibrinogen recorded on the first day (AUC: 0.83), and WBC, CRP, and fibrinogen recorded on the third day (AUC: 0.90), respectively." (PMID 38255436, 2024). "Moreover, CRP also showed better performance than PCT and another whole blood host response gene signature developed to distinguish sepsis from SIRS and uncomplicated infection." (PMID 39434093, 2024). "Inflammatory biomarkers, such as C-reactive protein (CRP), the erythrocyte sedimentation rate (ESR), and the systemic immune inflammation index (SII), have shown prognostic value in sepsis and infections, but their specific role in DNIs remains unclear." (PMID 39458054, 2024). "The laboratory indices revealed significant recovery in the levels of CRP (p < 0.001), PCT (p = 0.005), PT (p = 0.014), Fib (p < 0.001), and ALB (p = 0.037) were significantly recovered from S0 to S3 and S7 in patients with sepsis." (PMID 39060743, 2024). "Of the biomarkers, we showed here that PCT, CRP and SAA were useful in the diagnosis of sepsis." (PMID 38182736, 2024). "CRP levels above 100 mg/L were found to have a 100% positive predictive value and a 94% negative predictive value for the diagnosis of sepsis in 802 hemodialysis patients." (PMID 37016028, 2023). "Based we used multivariate MR, the effect of CRP on sepsis were independent of the effect of the exposure." (PMID 37662942, 2023). "Biomarkers such as CRP, PCT, and IL8 lack specificity for sepsis." (PMID 38053180, 2023). "Although PCT is more accurate in predicting severe infectious states when compared to CRP and other markers, it does not appear to be sensitive or specific enough to act as a reliable test for the recognition of sepsis." (PMID 37296721, 2023). "Non-survivors often presented with higher median PCT and CRP levels and severe complications, such as intracranial infection, cardiac dysfunction, respiratory failure, and severe sepsis or septic shock." (PMID 37964192, 2023). "The classic markers of sepsis, such as SOFA, CRP, PCT, and IL-6 on Days 0, 3, and 5 were compared." (PMID 37510189, 2023). "Although CRP is not a very specific test for sepsis, it does have a very high negative predictive value." (PMID 38138232, 2023). "Although non-specific for the diagnosis of sepsis, CRP and procalcitonin (PCT) are often used to detect inflammaion because of their high sensitivity." (PMID 36941681, 2023). "Furthermore, cell morphological features such as CRP, WBC count, lymphocytes, and cytokines were highly correlated with the clinical features used by physicians when making decisions in patients with sepsis." (PMID 37932249, 2023). "Since the CRP and procalcitonin levels remained consistent across patients with SIRS, sepsis, or septic shock, IGFBP-2 may be a superior marker." (PMID 38137505, 2023). "Their reasoning behind this omission is that the serum concentration of CRP has poor positive predictive value and that it has not been proven to be useful for diagnosing sepsis in asymptomatic neonates." (PMID 36834338, 2023).
Sepsis (continued). "Secondly, we were unable to discern any non-linear correlations among mcirbiota, CRP and sepsis, such as U-shaped, J shaped patterns." (PMID 37662942, 2023). "Serum procalcitonin (PCT) and high-sensitivity C-reactive protein (hs-CRP) are commonly utilized inflammatory markers during the clinical evaluation of septic patients, yet the role of biomarkers remains unspecified in the sepsis-3 definitions." (PMID 37215727, 2023). "In remission of sepsis (Days 7 to 10), serum YKL-40 (median (25th–75th): 24.1 (18.0–35.5) pg/mL) and CRP levels (median (25th–75th): 1.1 (0.40–1.9) mg/L) were significantly lower than levels upon admission (p = 0.004 and p < 0.001, respectively; Wilcoxon signed rank test)." (PMID 37238320, 2023). "First, it was not always possible to compare NEUT-RI with PCT and CRP in the first hours after the onset of sepsis (in the emergency room or in the hospital ward), since the latter were not always requested, and were only analyzed at admission to the ICU." (PMID 37238265, 2023). "Common clinical conditions like early onset sepsis and necrotizing enterocolitis were ruled out by relevant investigations like CRP, blood for culture and sensitivity, stool for occult blood, and chest and abdominal x-rays." (PMID 38161855, 2023). "Serum levels of C-reactive protein (CRP), the most widely used clinical marker for sepsis, are reduced in patients with liver cirrhosis, and this may limit the diagnostic utility of CRP." (PMID 37509420, 2023). "However, traditional screening methods and biomarkers such as C-reactive protein (CRP) and procalcitonin (PCT) lack specificity, which leads to the early diagnosis of sepsis is still a formidable challenge." (PMID 36812225, 2023). "CRP, usually a marker of inflammation or sepsis, was not significantly different between the two groups at any point in our study." (PMID 38077362, 2023). "Expression of sepsis-specific biomarkers PLXNB3, ITGB3, CETP, CMTM5 and PF4 correlated positively with each other at the Day1 time point and to a slightly lesser degree with MIA and CRP." (PMID 38332914, 2023). "Simultaneously, we observed a comparable postoperative inflammatory response in the POD+ and POD− groups, measured by the leucocyte count, CRP level, and procalcitonin, and no observed sepsis during the study period." (PMID 37629287, 2023). "We defined the favorable outcome criterion as weight gain, apyrexia, improvement of the general state, relief of pain, improvement in the classic inflammatory markers (CRP), and absence of vertebral deformities, neurological impairment, or sepsis." (PMID 37654630, 2023). "CRP and NLR have been used as markers of inflammation and immune system activity to predict disease activity, response to treatment or outcome in diseases such as cancer, sepsis, and cardiovascular diseases." (PMID 38104079, 2023). "Our study focussed on those during the recovery phase, and whilst there was a significant change in VO2 with IMT, markers of inflammation (CRP) and sepsis (SOFA) had no impact on VO2 at rest or with respiratory loading." (PMID 37415048, 2023). "Routine laboratory parameters most suitable to monitor sepsis, but not specific for septic encephalopathy, are C-reactive protein and procalcitonin." (PMID 37744876, 2023). "Compared with the previous meta-analysis, our results found that suPAR exhibited higher specificity than CRP and PCT, suggesting that it can better identify non-sepsis neonates and is more distinguishable than other biomarkers in newborns with different inflammatory diseases." (PMID 37181361, 2023). "However, in AKI patients with sepsis initiating CRRT, the prognostic value of CRP has rarely been noted." (PMID 36832265, 2023). "At present, the most commonly used biomarkers of sepsis in children are WBC, PCT and CRP." (PMID 38029254, 2023). "Specifically, the combination of IL6 and CRP has been suggested for identification of clinical sepsis in cases of negative bacterial culture." (PMID 37496672, 2023).